STK11 (serine/threonine kinase 11)
Diseases named in the same sentence as STK11 in open-access papers (continued):
Sharing a sentence is not in itself a finding about the gene and the disease.
cancer (continued). "In this study, we use a computational, transcriptomics-based pan-cancer approach to explore whether co-expression of PEBP1 and STK11 is associated with distinct TME profiles." (PMID 40806276, 2025). "Glucose metabolism-related molecules exhibited a complex and heterogenous pattern of correlations with PEBP1/STK11 co-expression, with both positive and negative associations observed across various cancer types." (PMID 40806276, 2025). "However, mutations in the mTOR gene, as well as loss of function mutations in TSC1, TSC2 (tuberous sclerosis proteins 1 and 2), or STK11 (serine/threonine kinase 11), make cancer cells sensitive to mTOR inhibitors." (PMID 39410536, 2024). "However, MTAP-loss CRC was also associated with a higher frequency of alterations in STK11 and KEAP1, which have been linked to immunotherapy resistance in NSCLC and pan-cancer cohorts." (PMID 38330461, 2024). "Therefore, future research and ongoing clinical trials will help us better understand the role of STK11 in cancer development and develop more effective treatment strategies." (PMID 38736875, 2024). "LKB1(STK11) is an oncogene implicated in the proliferation and migration of cancer cells." (PMID 38223257, 2024). "metMHN also infers multiple positive interactions between gene mutations and corresponding copy number alterations, exemplified by the interaction between EGFR (M) and amplification of EGFR/7p, as well as between STK11 (M) and deletion of STK11/19p—a pattern commonly seen across various cancers." (PMID 38940126, 2024). "Therefore, exploring the mechanism of action of STK11 in cancer patients is of great clinical value for a deeper understanding of the biological role and prognosis of STK11." (PMID 38736875, 2024). "Similarly, median OS was significantly shorter in patients with KRAS G12C–positive cancer with mSTK11-mKEAP1 vs STK11 WT-KEAP1 WT (5.0 vs 10.9 months; aHR, 2.20; 95% CI, 1.27–3.81; p = 0.005)." (PMID 37069542, 2023). "This study evaluated survival benefit with different 1L and 2L therapies in patients with KRAS G12C or WT cancer with or without STK11 and/or KEAP1 mutations, providing additional insights into these frequently co-occurring mutations." (PMID 37069542, 2023). "Nevertheless, when BRAF and KRAS mutations coexist with mutations of the tumour suppressor serine/threonine kinase 11 (STK11; also known as liver kinase B1, LKB1), cancer cells develop resistance to this dual inhibition, suggesting a new predictive biomarker to tailor combinatorial treatment." (PMID 37994501, 2023). "STK11 is a tumor suppressor gene that plays a role in tumorigenesis and cancer progression." (PMID 37356061, 2023). "Mechanistically, STK11 mutation leads to LKB1 loss, which then results in the suppression of stimulator of interferon genes (STING), whose activation is critical for anti-cancer immune response." (PMID 35281267, 2022). "The International Cancer of the Pancreas Screening Consortium indicates the screening for PDAC onset in patients with Peutz–Jeghers syndrome, with presence of STK11 mutation; with presence of a CDKN2A, BRCA1/2, or MMR mutation and with a first-degree relative affected with PDAC." (PMID 35205366, 2022).
cancer (continued). "The glucose-lowering drug metformin exerted anti-cancer effect and enhanced efficacy of chemotherapy in NSCLC with KRAS/STK11 co-mutation, yet it is unknown whether metformin may enhance ICI efficacy in STK11 mutant NSCLC." (PMID 35281267, 2022). "The heterogeneity in cancer status of PJS patients with the same STK11 variant may be partially explained by various mechanisms, in which STK11 is involved in tumorigenesis." (PMID 36033506, 2022). "For instance, STK11 (20.59% v 5.95%, odds ratio [OR] = 4.10), KEAP1 (15.38% v 4.61%, OR = 3.76), and MUTYH (4.96% v 2.35%, OR = 2.17) were more frequently mutated in KRASG12C-mutant tumors across all cancer types (P < .001 and FDR-P < .01 for all comparisons)." (PMID 35319967, 2022). "STK11 gene variations of PJS patients with cancers from 35 different families." (PMID 36033506, 2022). "In addition, the mutant STK11 gene can exist ubiquitously in all tissues, resulting in PJS patients facing the risk of many different cancers at indeterminate time points." (PMID 36033506, 2022). "PV were detected in 13 cancer predisposition genes including ATM (n=4), BLM (n=1), BRCA1 (n=1), BRCA2 (n=7), BRIP1 (n=1), CDKN2A (n=1), CHEK2 (n=9), FANCC (n=1), MUTYH (n=10), NBN (n=1), PALB2 (n=1), RAD51D (n=1) and STK11 (n=1)." (PMID 36091166, 2022). "The STK11 gene codes for liver kinase B1 (LKB1), a highly conserved serine/threonine kinase that acts as a sensor of cellular energy, giving it a special role in cellular metabolism, especially in cancer cells." (PMID 34831355, 2021). "Furthermore, the regulation of the expression of STK11 and its role in cancer cell proliferation remain very complex." (PMID 33572782, 2021). "Moreover, it was shown that STK11/LKB1 inactivation promotes cancer cell growth and survival via the upregulation of HIF-1α." (PMID 34831355, 2021). "Deletions in the FANCA, POLD1, and STK11 genes were observed in cancer patients only." (PMID 33431054, 2021). "Mutation of LKB1/STK11 leads to PJS, and such patients have an increased risk of several cancers." (PMID 33330475, 2020). "Pathogenic variants in STK11, also designated as LKB1, cause Peutz–Jeghers syndrome, which is a rare autosomal dominant disorder characterized by mucocutaneous pigmentation changes, polyposis, and a high risk of cancer." (PMID 32573125, 2020). "Here, the cumulative risk of any cancer was not significantly different between the cases with STK11/LKB1 mutation and those without the mutation (p = 0.43)." (PMID 30699894, 2019). "Loss of liver kinase B1 (LKB1, also known as serine/threonine kinase 11 or STK11) in non-small cell lung cancer (NSCLC) has been shown to enrich these tumors with KEAP1 mutations, making these cancers vulnerable to inhibition of NRF2-mediated antioxidant response." (PMID 31288436, 2019). "Loss-of-function mutations in STK11 also frequently occur in many sporadic (i.e. non-inherited) cancers, especially in the commonest form of lung cancer, adenocarcinoma (see also §6)." (PMID 31288625, 2019). "Of note, in HCT116, additional mutations in the APC, FGFR3 and STK11 genes have been described in the literature but are not included in the mutations that can be detected by the hotspot cancer panel v2." (PMID 28060956, 2017). "Mutual exclusivity analysis with genomic alteration data showed that STK11 alterations in cancer patients rarely co-occur with CDK4, CDKN2A, CDKN2B or RB1, supporting a role for STK11 in an oncogenic pathway that is intimately associated with cell cycle function." (PMID 28205554, 2017).
cancer (continued). "By contrast with STK11, mutations in PRKAA1 are infrequent (approximately 0.1% of all cancer cases) and around 80% of those that do occur are missense mutations that may not affect function (green symbols)." (PMID 26934201, 2016). "Our results suggest that the cell-type specific depleted signals in cancer cell lines may be under genomic alterations and can be located near genes associated with different types of cancer (i.e. FHIT, STK11, CDKN2A, CDKN2B)." (PMID 25522020, 2014). "For cancer genes which have been reported to have somatic or germline mutations in EOC, 3 were found to harbor copy deletions in serous histotype: PIK3R1, BRCA1, and STK11." (PMID 23078675, 2012). "Germline mutations in STK11 cause Peutz Jeghers Syndrome (PJS), an autosomal dominant disorder characterized by gastrointestinal hamartomatous polyps and a dramatically increased risk for the development of a variety of cancers." (PMID 22815934, 2012). "In carriers of LKB1/STK11 mutations, the risk of cancer was markedly elevated." (PMID 12865922, 2003). "Notably, CHOL and UCS cancers exclusively exhibited negative associations with all glucose metabolism-related genes that significantly correlated with PEBP1/STK11 co-expression, highlighting a distinct metabolic phenotype in these cancer types." (PMID 40806276, 2025). "In the present study, co-expression of PEBP1/STK11 was predominantly negatively correlated with several pro-inflammatory chemokines and immunosuppressive chemokine receptors, while showing positive correlations with anti-inflammatory chemokines in a cancer type dependent manner." (PMID 40806276, 2025). "Overall, our findings provide new evidence supporting the hypothesis that high PEBP1/STK11 co-expression may be involved in suppressing EMT-related features of cancer cells within the TME, which opens new avenues for hypothesis-driven research for the remodeling of the TME." (PMID 40806276, 2025). "Additionally, ACOX3, ACAD9, ACAD10, ACOT1, ACOT8, and DECR2 displayed positive associations with PEBP1/STK11 co-expression across various cancer types, highlighting a potential involvement in enhancing fatty acid metabolism in the context of PEBP1/STK11 expression." (PMID 40806276, 2025). "Moreover, our epithelial-to-mesenchymal transition (EMT) analysis revealed a consistent inverse association between PEBP1/STK11 co-expression and EMT marker genes, including SNAI1, SNAI2, FOXC2, ZEB1, and FN1, across most cancer types examined, thus underscoring a uniform anti-EMT signature." (PMID 40806276, 2025). "Patients without STK11 mutations had later symptom onset and potentially lower cancer risk." (PMID 39115133, 2024). "In our current study, we had explored the prognostic value of STK11 in NSCLC through two aspects of research, and combined with bioinformatics analysis, predicted and analyzed the potential mechanism of STK11 mutations causing deterioration of cancer biological behavior." (PMID 38736875, 2024). "Interestingly, while mSTK11-KEAP1 WT was also more prevalent in patients with KRAS G12C-positive cancer vs KRAS WT cancer (13.0% vs 9.0%; p = 0.05), STK11 WT-mKEAP1 was more prevalent in patients with KRAS WT cancer vs KRAS G12C-positive cancer (15.0% vs 7.0%; p < 0.001)." (PMID 37069542, 2023). "Aiming to develop the therapeutic drugs, we performed Genomics of Drug Sensitivity in Cancer (GDSC) data to identify the potential therapeutic candidate and the results showed that Nutlin-3a(-) may be a sensitive drug for LUAD cases harboring STK11 mutations." (PMID 33425731, 2020). "Hence, STK11 could control the regulation of important hallmarks of cancer such as cellular energetics and cell proliferation, among others." (PMID 32911741, 2020). "The GDSC screening results revealed that Nutlin-3a(-) may exhibit sensitivity for LUAD with STK11 mutations, while not exhibiting sensitivity to other cancer types with STK11 mutations." (PMID 33425731, 2020).
cancer (continued). "In addition, somatic mutations in STK11 are now known to occur quite frequently in non-inherited cancers." (PMID 33375416, 2020). "Moreover, AMPK could be indirectly activated by high concentration of intracellular Ca2+, according to studies using STK11 knockout HeLa cancer cells." (PMID 33070285, 2020). "We were also able to examine the known CRC-predisposing genes (apart from STK11) and found no known pathogenic variants in this family, suggesting that other novel genes may predispose to this rare subtype of cancer in the colon." (PMID 32357859, 2020). "Therefore, we hypothesize that STK11 and NUAK1 are selectively essential for cell cycle progression and DNA damage repair in PTEN-deficient cancers." (PMID 29566768, 2018). "Up to now, therapeutic approaches for STK11 mutant cancer were mainly conducted through the restoration of the mTOR pathway using mTOR inhibitors or phenformin, an analog of metformin, without taking into account the potential dual effect of STK11 mutations." (PMID 26625312, 2017). "Liver kinase B1 (LKB1, also known as STK11) was first identified as the causal mutation in Peutz–Jeghers Syndrome (PJS), a rare inherited autosomal dominant disorder characterised by the development of benign gastrointestinal hamartomas and the early onset of cancer." (PMID 26196184, 2015). "Other tumor suppressor genes (KEAP1, STK11), which can impair immunotherapy responses in KRAS-mutant cancers, showed slightly increased frequency from baseline to progression." (PMID 40244261, 2025). "PEBP1/STK11 co-expression was further shown to modify the mechanical and structural components of the TME across human cancers." (PMID 40806276, 2025). "The cancers exhibiting the strongest positive correlations between anti-inflammatory chemokine genes and PEBP1/STK11 co-expression were found in the urinary, respiratory, and endocrine systems." (PMID 40806276, 2025). "Overall survival (OS) and Hazard Ratio (HR) analyses were conducted within a pan-cancer framework to assess the impact and the putative clinical significance of the co-expression of the PEBP1 and STK11 transcripts." (PMID 40806276, 2025). "In recent years, keywords like LKB1/STK11, surveillance, and screening have dominated, indicating a strong current emphasis on the molecular basis of PJS and strategies to detect cancers early." (PMID 40989965, 2025). "Therefore, restoring STK11 function or targeting its downstream effectors may contribute to reversing immunosuppressive characteristics and provide a potential therapeutic option for STK11-low cancers." (PMID 41051525, 2025). "STK11, also named LKB1, controls the activity of AMP-activated protein kinase (AMPK) by phosphorylation and downregulates mTOR signaling, thereby inhibiting cancer cell proliferation and protein synthesis." (PMID 37351538, 2023). "STK11 WT-mKEAP1 and STK11 WT-KEAP1 WT were more prevalent in patients with KRAS WT cancer, than those with KRAS G12C-positive cancer (15.0% vs 8.1%; p = 0.01 and 65.9% vs 53.4%, p = 0.02, respectively)." (PMID 37069542, 2023).
cancer (continued). "Other high-penetrant cancer genes BRCA1, APC, STK11 and moderate-penetrant genes BRIP1, CDKN2A, FANCI and MET had a similar frequency 1 (5.8%)." (PMID 37277882, 2023). "The genomic profiling of GC PNM also identified alterations in other cancer-related genes, including NOTCH1, NOTCH2, NF1, and STK11." (PMID 35515115, 2022). "The tumor suppressor LKB1 (also known as serine/threonine kinase 11; STK11) is frequently inactivated in several human cancer types and governs differentiation in both normal and neoplastic settings." (PMID 35228570, 2022). "In three patients, we detected fusions involving a cancer-related gene, such as STK11 and KDM6A, quoted as altered in MPM in the Cosmic database (release v91), or TFG reported in fusions in other cancers." (PMID 34261524, 2021). "STK11, a kinase involved in the regulation of ADORA1, was aberrantly expressed in various tumors and played a role in promoting cancer cell adhesion and angiogenesis." (PMID 34093805, 2021). "Finally, our data established miR-100-3p to be a bona fide negative regulator of STK11, and a potential role for miR-100-3p as an oncomiR in this type of cancer via the inactivation of tumor suppressor STK11 can be proposed, although further assays may be necessary." (PMID 32911741, 2020). "STK11 has also been reported to engage with ATG proteins and promote autophagy in cancer cells modulating the effects of anti-cancer agents." (PMID 32963809, 2020). "A recent study demonstrated that PPi hubs can be identified for a variety of cancer-related genes, including MYC, STK11, RASSF1, and CDK4." (PMID 28362357, 2017). "Identification of the STK11-SNP is based on analyses of the MSF in which a number of women in the maternal lineage had comorbidities of tumors, cancers, cysts, or polyps (TCCP)." (PMID 25694554, 2015). "In contrast, a uniform negative association with PEBP1/STK11 co-expression was found in most of the genes encoding TNF ligands (ENFSF13B, TNFSF4, TNFSF9, TNFSF14, TNFSF18, and TNFSF15) in almost all cancer types." (PMID 40806276, 2025). "CAB39, a component of a trimeric complex including serine/threonine kinase 11 (STK11) and STE20-related adaptor alpha (STRAD), has been studied in the context of cancer progression, but with unknown function during SARS-CoV-2 infection." (PMID 40833112, 2025). "Ten patients had germline mutations affecting cancer predisposition genes not typically linked to WT: CHEK2 in 4 children, and BLM, BRCA2, CDKN2A, FMN2, PIK3C3, and STK11 in one patient each." (PMID 40340749, 2025). "Laminins, key components of the extracellular matrix (ECM), exhibited predominantly negative correlations with PEBP1/STK11 co-expression across most cancer types." (PMID 40806276, 2025). "Genes like PGK1, PFKP, HK2, and LDHA, that are involved in metabolic reprogramming of cancer cells by enhancing glycolysis have a negative correlation with PEBP1/STK11 co-expression." (PMID 40806276, 2025). "Our analysis indicated that tyrosine phosphatase PTP4A1 (also called PRL1, phosphatase of regenerating liver 1) may have an oncogenic role in STK11-inactivated NSCLC and that PTP4A1-dependent effects of FTIs in these cancers should be further evaluated." (PMID 39995872, 2025). "In these cell lines, KYNU was upregulated even in the absence of KEAP1/STK11 co-mutation, indicating that KYNU regulation varies across cancer lineages." (PMID 40427178, 2025).